SNORD45C (small nucleolar RNA, C/D box 45C)
Synonyms: U45C
Gene: Small nucleolar RNA gene on chromosome 1 (75,787,072 to 75,787,150, forward strand). Ensembl gene ENSG00000206620.
Gene Ontology:
Biological process: RNA processing
Cellular component: nucleolus
Homologues: Orthologues: chimpanzee SNORD45C (100% identical), macaque SNORD45C (97% identical), rabbit SNORD45C (97% identical), pig SNORD45C (96% identical). Paralogues in human: SNORD45A (87% identical), SNORD45B (77% identical).